RPL21P10 (ribosomal protein L21 pseudogene 10)
Synonyms: RPL21_49_1395
Gene: Processed pseudogene on chromosome 14 (77,683,202 to 77,683,989, reverse strand). Ensembl gene ENSG00000239272.
Diseases named in the same sentence as RPL21P10 in open-access papers:
RPL21P10 is named in the same sentence as 1 disease in open-access papers, as found by Europe PMC text mining. Sharing a sentence is not in itself a finding about the gene and the disease.
RPL21P10 shares sentences with these, for which no sentence is quoted: neuroblastoma (1 paper).